PPA1 (inorganic pyrophosphatase 1)
Diseases named in the same sentence as PPA1 in open-access papers (continued):
Sharing a sentence is not in itself a finding about the gene and the disease.
lung carcinoma (5 papers, 2015 to 2022). "The previous study in our lab22 found that the expression of PPA1 was significantly higher in lung cancer, and its expression was associated with age, smoking status, and tumor size, which suggests that PPA1 plays an important role in lung tumorigenesis and progression." (PMID 31551407, 2019). "Our previous data showed that PPA1 expression is associated with tumor size in lung cancer, which may have resulted from apoptosis." (PMID 27666431, 2016). "Here, we disclosed that PPA1 expression is markedly upregulated in lung carcinoma tissue versus normal lung tissue." (PMID 31551407, 2019). "Here, we found that PPA1 was upregulated in lung carcinoma versus normal tissue, and its expression was correlated with patient survival." (PMID 31551407, 2019). "And this paper mainly discusses the role of PPA1 to the proliferation and apoptosis in lung cancer, and other functions of PPA1 remains further study." (PMID 27666431, 2016). "We found that PPA1 expression was significantly increased in the primary tumors of lung cancer patients compared with normal lung tissue in GSE40275 (P = 0.014) and GSE43346 (P = 0.001)." (PMID 27666431, 2016). "Additionally, this significant increase in PPA1 expression inhibits apoptosis in lung cancer cells by dephosphorylating p-JNK1 at the peptide level." (PMID 36505776, 2022). "Together, these results indicated that PPA1 was upregulated in lung carcinoma tissues." (PMID 31551407, 2019). "In lung cancer, lesions greater than 5 cm (n = 61) exhibited stronger expression of PPA1 than those less than or equal to 5 cm (n = 124; P = 0.018); patients aged less than 60 years (n = 105) exhibited stronger expression of PPA1 than those 60 years of age and older (n = 77; P = 0.004)." (PMID 27666431, 2016). "Additionally, this trend seen in lung cancer was consistent with the data obtained by quantitative RT‐PCR, which indicates that PPA1 expression is up‐regulated at both the mRNA and protein levels in lung cancer." (PMID 27666431, 2016). "Finally, the decreased expression of PPA1 may serve as a molecular target for the treatment of ovarian and lung cancers." (PMID 27666431, 2016). "However, the specific role of PPA1 in lung cancer or NSCLC progression remains unclear." (PMID 31551407, 2019). "In conclusion, our present study demonstrated that the expression of PPA1 was markedly upregulated in lung carcinoma tissue versus normal lung tissue." (PMID 31551407, 2019).
colon cancer (3 papers, 2017 to 2021). "The results above demonstrated that overexpression of PPA1 promote proliferation of colon cancer cells and we next want to explore the underlying mechanisms of its functions." (PMID 28938583, 2017). "In contrast, PPA1-silencing significantly down-regulated the cell proliferation, while JNK inhibitor can impair this antiproliferation effects, indicating that PPA1's functions in colon cancer is at least partially through regulating JNK activity." (PMID 28938583, 2017). "In the current study, we used RT-qCR, Western Blot and immunohistochemical (IHC) staining to explore the expression of PPA1 in 113 paired colon cancer tissues and adjacent normal tissues, which revealed that PPA1 was correlated with lymph node metastasis." (PMID 28938583, 2017). "Western Bolt results showed that PPA1 was higher expressed in colon cancer cell lines than that in normal epithelial CCD-18Co cells." (PMID 28938583, 2017). "Univariate and multivariate analyses verified the clinical significance of PPA1 in predicting clinical outcomes of colon cancer patients." (PMID 28938583, 2017). "In the present study, we analyzed the expression patterns of PPA1 in colon cancer for the first time, and tried to get insights into its functional pathways through enzymatic experiments, gene transfections and biological studies." (PMID 28938583, 2017). "To further elucidate PPA1's relation to colon cancer aggression, we firstly explored its expression in different cell lines." (PMID 28938583, 2017). "And PPA1 was demonstrated to be positively correlated with lymph node metastasis, indicating the oncogenetic role of this protein in colon cancer progression." (PMID 28938583, 2017). "Next, we carried out CCK-8 assay to investigate the potential role of PPA1 in regulating proliferation of colon cancer cells." (PMID 28938583, 2017). "In all, our study not only demonstrated the expression and predictive value of PPA1 in colon cancer prognosis, but also verified its role as a pJNK phosphatase which highlight its significance as a potential chemotherapy target." (PMID 28938583, 2017). "SW480 cells showed highest PPA1 expression while HT29 showed lowest PPA1 expression among the colon cancer cell lines we tested." (PMID 28938583, 2017). "In the current study, we identified the up-regulated expression of PPA1 in colon cancer tissues than that in adjacent normal tissues." (PMID 28938583, 2017). "Kaplan-Meier analysis revealed that colon cancers expressing high PPA1 levels ((++) or (+++)) correlated with decreased overall survival compared to the low PPA1 group (log-rank test P=0.005)." (PMID 28938583, 2017). "Further, univariate and multivariate analyses revealed that PPA1 was an independent prognostic factor for the OS of colon cancer patients." (PMID 28938583, 2017). "We investigated whether the OS of colon cancer patients may be related with PPA1 in tumor tissues, as well as with other clinicopathologic factors." (PMID 28938583, 2017). "In addition, PPA1-D117A overexpression showed no significantly effect on either those protein levels or cell proliferation capacity, indicating that PPA1 catalytic activity was essential for its oncogenetic functions in colon cancer cells." (PMID 28938583, 2017). "Taken together, these results implied that PPA1 interacts either directly or indirectly with active JNK (pJNK), and that PPA1 may regulate cellular proliferation in colon cancer cells via the JNK signaling pathway." (PMID 28938583, 2017). "Results from cellular experiments indicated that PPA1 may negatively regulate pJNK levels and we further performed IHC towards pJNK in colon cancer tissues, which showed nucleus location in cancer cells." (PMID 28938583, 2017). "Therefore, we believe that PPA1 can both regulate the cell apoptosis and proliferation in colon cancer cells." (PMID 28938583, 2017). "Moreover, the PPA1 expression and its clinical significance in colon cancer haven't been investigated." (PMID 28938583, 2017).
colon cancer (continued). "Thus, PPA1 catalytic activity is required in regulating colon cancer cell proliferation." (PMID 28938583, 2017). "Meanwhile, IHC results identified the negative correlation between pJNK and PPA1 expression levels in colon cancer tissues." (PMID 28938583, 2017). "Importantly, PPA1-DOX exhibits a significantly improved antitumor activity in vivo, most likely by alleviating chemotherapeutic resistance of DOX and enhancing immune response in colon cancer." (PMID 34858817, 2021).
neuroblastoma (2 papers, 2013 to 2016). Neuroblastoma (NB) is the most common solid, extracranial childhood tumor. "We examined the role of PPA1 in neuronal differentiation using the loss and gain of function analysis in the mouse neuroblastoma cell line, N1E115." (PMID 23626709, 2013). "In the present study, we examined the functional role of PPA1 in the neuronal cell using the neuroblastoma cell line, N1E115." (PMID 23626709, 2013).
non-small cell lung carcinoma (2 papers, 2019 to 2021). A group of at least three distinct histological types of lung cancer, including non-small cell squamous cell carcinoma, adenocarcinoma, and large cell carcinoma. "We also found that the non-small cell lung cancer (NSCLC) cell lines show increased PPA1 expression levels versus normal lung cell line control." (PMID 31551407, 2019).
ovarian tumor (2 papers, 2016 to 2017). "The present study was designed to evaluate PPA1 expression in different types of human ovarian tumor tissues and normal ovarian tissues to investigate how PPA1 functions." (PMID 29100310, 2017). "Taken together, our data demonstrated that PPA1 is up‐regulated in lung and ovarian tumor tissues." (PMID 27666431, 2016).
Alzheimer disease (1 paper, 2025). A progressive, neurodegenerative disease characterized by loss of function and death of nerve cells in several areas of the brain leading to loss of cognitive function such as memory and language. "Calculation deficits have been reported in pwPPA and Alzheimer’s disease, especially when there is involvement of the inferior parietal lobe, as is the case for participants PPA2 and PPA4, and suspected in PPA1 and PPA3 based on clinical and biomarker findings." (PMID 41300200, 2025).
benign ovarian tumors (1 paper, 2017). "First, compared to normal ovarian tissues and benign ovarian tumors, we found that PPA1 was overexpressed in human EOC tissues." (PMID 29100310, 2017).
colorectal tumors (1 paper, 2024). "One example of the role of c-PPase is the heightened expression of PPA1, the housekeeping isoform of c-PPase in humans, in colorectal tumors." (PMID 38938619, 2024).
endometriosis (1 paper, 2014). The growth of functional endometrial tissue in anatomic sites outside the uterine body. "The levels of GRP78 and PPA1 expression were higher in the GnRHa- (untreated) group compared with the GnRHa + (GnRHa-treated) group (P <0.05), while EFHA2 and TGM2 expression significantly increased in endometriosis patients after GnRHa treatment (P <0.05)." (PMID 25367189, 2014).
epithelial ovarian tumors (1 paper, 2025). "Similarly, inorganic pyrophosphatase (PPA1) is markedly upregulated in epithelial ovarian tumors." (PMID 40862711, 2025).
galactosemia (1 paper, 2023). "Unresolved abnormalities in galactosemia screening might result in the identification of more individuals with PPA1 deficiency, a newly discovered inborn metabolic disorder (IMD)." (PMID 37999237, 2023).
Glucose intolerance (1 paper, 2025). Glucose intolerance (GI) can be defined as dysglycemia that comprises both prediabetes and diabetes. "Beyond oncogenesis, PPA1 regulates metabolic homeostasis: PPA1 knockout mice develop glucose intolerance and insulin resistance under high-fat diets, while yeast PPA1 silencing disrupts NAD+ metabolism, triggering cell cycle arrest and autophagic death." (PMID 41315223, 2025).
Hyperbilirubinemia (1 paper, 2023). An increased amount of bilirubin in the blood. "Although hyperbilirubinemia is a quite common finding in neonates, it is speculated to be related to PPA1 deficiency." (PMID 37999237, 2023).
intrahepatic cholangiocarcinoma (1 paper, 2022). A carcinoma that arises from the intrahepatic bile duct epithelium in any site of the intrahepatic biliary tree. "PPA1 expression is significantly associated with intrahepatic cholangiocarcinoma (ICC) development, including tumor size, lymph node metastasis, differentiation, and TNM stage." (PMID 36505776, 2022).
lysosomal storage disease (1 paper, 2026). A metabolic disorder caused by mutations in proteins critical for lysosomal function, including lysosomal enzymes, lysosomal integral membrane proteins, and proteins involved in the post-translational modification and trafficking of lysosomal proteins. "We generated viable hypomorphic alleles of PPa1 through random mutagenesis in mice and unexpectedly found that PPa1 insufficiency causes a lysosomal storage disease of the bone marrow." (PMID 41889845, 2026).
pseudogout (1 paper, 2016). "It is well known that PPA1 is linked to pseudogout, which is a calcium pyrophosphate dihydrate deposition disease that results when calcium pyrophosphate crystals are formed in joints, which induces pain and restricts mobility." (PMID 27666431, 2016).
cancer (20 papers, 2011 to 2025). A tumor composed of atypical neoplastic, often pleomorphic cells that invade other tissues. "Recently, PPA1 was found to be associated with cell migration, invasion and proliferation of cancer cells." (PMID 25923237, 2015). "PPA1 encodes an inorganic pyrophosphatase dysregulated in several cancers." (PMID 39027151, 2024). "Therefore, the association of PPA1 to cell proliferation and metastasis in cancer is undisputable." (PMID 34595179, 2021). "As an enzyme involved in energy metabolism, PPA1 is prominently expressed in various malignant tumors and contributes to tumor progression through multiple pathways." (PMID 40862051, 2025). "Pyrophosphatase 1(PPA1), an energy-metabolizing enzyme, has been observed to be upregulated in multiple cancers and implicated in tumorigenesis and progression." (PMID 41315223, 2025). "Further, PPA1 is a potential biomarker to predict survival in patients with cancer, where the assessment of its transcriptional regulation can provide an in-depth understanding." (PMID 36505776, 2022). "PPA1 differential expression in normal tissues and corresponding malignant tumors indicates its potential as a molecular target for screening, diagnosing, and treating malignancies as well as predicting patient prognosis." (PMID 36505776, 2022). "The results indicated that PPA1 was highly expressed in tumor tissues compared to normal/para-carcinoma tissues." (PMID 34595179, 2021). "To examine the expression of PPA1 in tumor tissue, we first performed IHC on paraffin‐embedded carcinomas, including 12 different types of tumors, from 274 patients." (PMID 27666431, 2016). "Further in depth studies will elucidate more on the PPA1 gene regulation in cancer and its role in carcinogenesis." (PMID 25923237, 2015). "Among them, those highly correlated with different pathological stages are LANCL3, MFAP2 and PPA1, showing consistent up- and down-regulation, respectively, along with cancer progression." (PMID 21445269, 2011). "Moreover, other genes upregulated in distinct but also specific stimuli like PPA1, GADD45B, C1D, TRPV2 and RPS14 were associated with DDR, cancer and apoptosis." (PMID 39623312, 2024). "Recently, PPA1 was found to be associated with cell migration, invasion and proliferation of cancer cells, although no clearly mechanism or systematic clinical study was reported." (PMID 28938583, 2017). "However, the elucidation of the function and mechanism of PPA1 in the development of many types of cancers and its potential as a target of tumor therapy requires further exploration." (PMID 27666431, 2016). "PPA1 is deregulated in several cancers and differentially expressed in rat and mice liver with age." (PMID 25923237, 2015). "Moreover, we suggest the PPA1 protein as a potential new biomarker for metastasis in this cancer." (PMID 26948660, 2016). "However, whether PPA2 has a similar prognostic value to PPA1 in cancer remains unknown." (PMID 34567842, 2021). "Inorganic pyrophosphatase (PPA1), an important pyrophosphate hydrolysing enzyme is also known to be overexpressed in many types of cancer." (PMID 25923237, 2015). "The overexpressed proteins, including actinin α1 isoform (ACTN1), annexin A5 (ANXA5), cathepsin D (CTSD), F-actin-capping protein subunit β (CAPZB), inorganic pyrophosphatase (PPA1), and tubulin α1c chain (TUBA1C), are related to cellular structure, growth, or cancer cell invasion." (PMID 38249992, 2024). "Since it has been reported that activated JNK showed antiproliferation effects in cancer cells, we then used JNK specific inhibitor (SP600125) to see whether it can affect the role of PPA1." (PMID 28938583, 2017). "Notably, PPA1 was considered a negative prognostic marker of gastric cancer and participated in cancer-related metabolic alterations." (PMID 34595179, 2021).
tumor (17 papers, 2012 to 2025). "In addition, since the pathological grade and clinical stage of tumor were closely correlate with tumor malignancy and progression, we investigated the associations between PPA1 expression and clinicopathological characteristics." (PMID 34595179, 2021). "However, whether PPA1 directly influences tumor metabolism and the precise mechanisms underlying its potential oncogenic effects remain poorly understood." (PMID 41315223, 2025). "Our study revealed that PPA1 is highly expressed in CRC epithelial cells and is significantly associated with advanced tumor size, lymph node status, TNM stage, and reduced overall survival in patients." (PMID 41315223, 2025). "We found that elevated PPA1 expression correlates with larger tumor size, lymph node status, advanced TNM stage, and poor patient prognosis." (PMID 41315223, 2025). "Western Blotting analysis of tumor tissues revealed elevated E-cadherin and decreased N-cadherin expression in the Sh-PPA1 group compared to the Sh-NC group, whereas the OE-PPA1 group exhibited the opposite trend compared to the OE-NC group." (PMID 41315223, 2025). "Growth curve analysis revealed that PPA1 knockdown significantly inhibited subcutaneous tumor growth, with the Sh-PPA1 group exhibiting smaller tumor volumes and lower weights compared to the Sh-NC group." (PMID 41315223, 2025). "Conversely, PPA1 overexpression markedly promoted tumor growth, as evidenced by larger tumor volumes and higher weights in the OE-PPA1 group versus the OE-NC group." (PMID 41315223, 2025). "Herein, we describe the signaling pathways through which PPA1 regulates malignant tumor progression and provide new insights to establish PPA1 as a biomarker for tumor diagnosis." (PMID 36505776, 2022). "The widespread expression of a protein such as PPA1 in tumor tissues and cells implies that it plays an extremely important role in the development of this malignancy." (PMID 36505776, 2022). "Analyzing the differences between normal tissues and tumor tissues in terms of PPA1 enzymatic activity is beneficial to further investigate the potential role of PPA1 in the metabolic process for tumors." (PMID 36505776, 2022). "Owing to the extreme adaptability of malignancies, enhanced PPA1 expression suggests its requirement for tumor survival." (PMID 36505776, 2022). "We developed a novel synergistic strategy by conjugating PPA1 to doxorubicin (DOX) with a pH sensitive linker that can trigger the release of DOX near acidic tumor tissues." (PMID 34858817, 2021). "Recently, a novel proteolysis resistant PD-L1-targeted polypeptide, PPA1, has appeared as an outstanding tumor-targeting modification of synergistic drug conjugate for effective anti-tumor treatment." (PMID 34858817, 2021). "Taken together, these results confirmed that PPA1 promoted tumor growth and metastasis via the PI3K/AKT/GSK3β signaling in vivo." (PMID 34595179, 2021). "A novel polypeptide PPA1 has been reported that it can bind PD-L1 in vitro and inhibit the tumor growth in CT26 bearing mice by disrupting the PD-1/PD-L1 interaction." (PMID 34858817, 2021). "As expected, a remarkably higher tumor-specific enrichment and lower distribution in other non-tumor major tissues was achieved by the PPA1-DOX construct, as compared with the RAN-DOX construct." (PMID 34858817, 2021).